LRIT3 (leucine rich repeat, Ig-like and transmembrane domains 3)
Description:
Plays a role in the synapse formation and synaptic transmission between cone photoreceptor cells and retinal bipolar cells (By similarity). Required for normal transmission of a light-evoked stimulus from the cone photoreceptor cells to the ON-bipolar cells and ON-ganglion cells in the inner retina. Required in retinal ON-bipolar cells for normal localization of the cation channel TRPM1 at dendrite tips (By similarity). Seems to play a specific role in synaptic contacts made by ON-bipolar cells with cone photoreceptor pedicles (By similarity). May also have a role in cone synapse formation (By similarity). Might facilitate FGFR1 exit from the endoplasmic reticulum to the Golgi. Could be a regulator of the FGFRs.
Synonyms: FLJ44691; FIGLER4; CSNB1F
Tractability: Antibody: UniProt predicts a signal peptide or a membrane-spanning region.
Gene: Protein-coding gene on chromosome 4 (109,846,013 to 109,872,315, forward strand). Ensembl gene ENSG00000183423.
Subcellular location: Cell projection, dendrite; Perikaryon; Endoplasmic reticulum membrane
Subcellular location (Human Protein Atlas): Cytosol; Mitochondria; Nucleoplasm
Gene Ontology:
Biological process: regulation of fibroblast growth factor receptor signaling pathway
Cellular component: perikaryon; cell tip; dendrite; endoplasmic reticulum membrane
Genetic constraint (gnomAD): Loss-of-function variants: 20 observed, 25.4 expected, observed/expected ratio (o/e) 0.79, 90% interval 0.55 to 1.14. The upper end of that interval is the gene's LOEUF score, 1.14, which puts it in group 5 of 6, group 1 being the genes least tolerant of losing a copy. Missense variants: 759 observed, 800.7 expected, observed/expected ratio (o/e) 0.95, 90% interval 0.89 to 1.01. Synonymous variants: 287 observed, 302.89 expected, observed/expected ratio (o/e) 0.95, 90% interval 0.86 to 1.04.
Homologues: Orthologues: chimpanzee LRIT3 (99% identical), macaque LRIT3 (95% identical), rabbit LRIT3 (81% identical), dog LRIT3 (80% identical), pig LRIT3 (78% identical), rat Lrit3 (73% identical), guinea pig LRIT3 (72% identical), mouse Lrit3 (72% identical), tropical clawed frog lrit3 (52% identical), zebrafish lrit3a (45% identical), zebrafish lrit3b (27% identical), Drosophila melanogaster kek3 (14% identical), and 3 more. Paralogues in human: LRIT1 (32% identical), LRIG3 (19% identical), LRIG2 (19% identical), LRIG1 (18% identical), LGR5 (18% identical), LGR6 (15% identical), LGR4 (15% identical), ELFN2 (13% identical), LGI3 (12% identical), LRRC24 (12% identical), TRIL (12% identical), LGI1 (11% identical), and 10 more.
Diseases named in the same sentence as LRIT3 in open-access papers:
LRIT3 is named in the same sentence as 7 diseases in open-access papers, as found by Europe PMC text mining. Sharing a sentence is not in itself a finding about the gene and the disease. The quoted sentences say what the papers report.
congenital stationary night blindness (5 papers, 2019 to 2026). "LRIT3 is a leucine-rich repeat (LRR) protein that is expressed in the retina, and its absence causes complete congenital stationary night blindness (cCSNB), a genetically diverse disorder characterized by impaired low-light vision, myopia, and nystagmus." (PMID 42055330, 2026). "Variants in LRIT3, GRK1, and RLBP1 were previously reported to be associated with autosomal recessive or X-linked congenital stationary night blindness." (PMID 40365019, 2025). "These systemic syndromes can be caused by a series of genes, including NYX, CACNA1F, GRM6, and LRIT3, responsible for congenital stationary night blindness (CSNB); COL2A1, COL11A1, COL9A1, and COL9A2, responsible for Stickler syndrome; and FBN1, responsible for Marfan syndrome." (PMID 36980859, 2023).
myopia (3 papers, 2025 to 2026). "Despite the paucity of reported patients with LRIT3-related CSNB, the published cases find high myopia to be a consistent feature." (PMID 41153400, 2025). "Genes involved in the depolarization of ON bipolar cells include TRPM1, NYX, GPR179—detected in our described patient—and LRIT3, which, when damaged, similarly cause a negative ERG and are associated with high myopia." (PMID 40004769, 2025).
cholangiocarcinoma (1 paper, 2022). A carcinoma that arises from the intrahepatic biliary tree (intrahepatic cholangiocarcinoma) or from the junction, or adjacent to the junction, of the right and left hepatic ducts (hilar cholangiocarcinoma). "In fact, such a hypothesis is supported by the fact that LRIT3 is a regulator of FGFR1, one of the driver genes of cholangiocarcinoma." (PMID 35382169, 2022).
cancer (1 paper, 2022). A tumor composed of atypical neoplastic, often pleomorphic cells that invade other tissues. "Curiously, although LRIT3 has not been reported as a cancer driver, it showed the highest mutant allele frequency in our case with two-hit mutations, a nonsense mutation, and an LOH; therefore, we cannot exclude the notion that such mutations were involved in the formation of IPNB." (PMID 35382169, 2022).
LRIT3 also shares sentences with these, for which no sentence is quoted: Marfan syndrome (1 paper); Nystagmus (1); Stickler syndrome (1).